RNY4P17 (RNY4 pseudogene 17)
Gene: Miscellaneous RNA gene on chromosome 4 (169,005,249 to 169,005,344, forward strand). Ensembl gene ENSG00000201818.
Homologues: Orthologues: chimpanzee Y_RNA (97% identical), guinea pig Y_RNA (86% identical). Paralogues in human: RNY4 (92% identical), RNY4P6 (90% identical), RNY4P7 (89% identical), RNY4P24 (88% identical), Y_RNA (88% identical), RNY4P13 (86% identical), RNY4P14 (86% identical), Y_RNA (86% identical), RNY4P10 (85% identical), RNY4P19 (85% identical), RNY4P3 (85% identical), RNY4P9 (85% identical), and 91 more.